NF1 (neurofibromin 1)
Diseases named in the same sentence as NF1 in open-access papers (continued):
Sharing a sentence is not in itself a finding about the gene and the disease.
neuroblastoma (continued). "NF1 protein levels in neuroblastoma cell lines were determined using Western blot assays." (PMID 26925841, 2016). "ERK pathway activation has been previously observed in NF1 mutated neuroblastoma, but not previously found correlated with MYCN expression levels." (PMID 26673823, 2015). "Second, ALK functions as an oncogene and NF1 as a tumor suppressor in neuroblastoma." (PMID 24278035, 2013). "To test this hypothesis, we assembled a panel of RAS- and NF1-altered neuroblastoma cell lines." (PMID 39001383, 2024). "We hypothesized that this combination would be similarly effective in neuroblastoma with hyperactivity of the RAS/MAPK pathway, either through mutation of one of the RAS isoforms or through inactivation of the RAS GTPase activating protein, NF1." (PMID 39001383, 2024). "Previous studies have shown that the genetic knockdown of IGF1R expression using shRNA decreased the transwell invasion of neuroblastoma cells such as IMR32 and SH-SY5Y; however, the effect of IGF1R inhibition on RAS- or NF1-altered neuroblastoma cell invasion is unknown." (PMID 39001383, 2024). "However, further investigation of the mechanism in the future may help to develop new ways of overcoming the feedback reactivating of the RAS/MAPK pathway in NF1 wild type neuroblastomas to render them sensitive to MEK inhibitors in general." (PMID 35689207, 2022). "Moreover, we identified hypersensitivity to MEK inhibition as a novel collateral sensitivity specific to NF1 loss, which may represent a clinically actionable therapeutic strategy for ALK-inhibitor resistant neuroblastoma." (PMID 35689207, 2022). "To evaluate whether gene expression of RAS/MAPK pathway members was associated with neuroblastoma patient outcomes, we evaluated the associations of NF1 and MEK1/2 gene expression with neuroblastoma patient outcomes using results from microarray analyses of neuroblastoma tumors." (PMID 26925841, 2016). "Thus, the overexpression of MYCN blocks the differentiation of sympathoadrenal precursor cells, leaving them vulnerable to the potentiating effects of nf1 loss on RAS pathway activation, which in turn leads to the marked increased in neuroblastoma penetrance and growth rate." (PMID 27130733, 2016). "Thus, we hypothesized that NF1 expression in neuroblastoma tumor cells might influence responses to binimetinib treatment." (PMID 26925841, 2016). "• Binimetinib is effective in preclinical models of neuroblastoma tumors with low NF1 expression.• Binimetinib and CDK4/6 inhibitors are synergistic in preclinical models of neuroblastoma." (PMID 40115016, 2025). "TT sensitivity predictors were identified in 120/304 cases (39.5%): Tier II in 83 patients, Tier IB in 32 patients (almost always ALK in neuroblastoma, n = 31) and Tier IA in 5 patients: BRAF p.V600E (n = 3) and NF1 aberrations (n = 2)." (PMID 41373618, 2025). "Study (a): a retrospective analysis of questionnaire-based data [years 1979–2017] derived from the databases of the Italian Registry for Neuroblastoma (RINB) of the Italian Society of Pediatric Onco-Haematology (AIEOP); and Study (b): a systematic review search on NF1/NB co-occurrence." (PMID 36405824, 2022). "In addition to the prognostic importance of PBX1, NF1, and HOXC9 proteins, our results demonstrated that PBX1 could be used for the prediction of the clinical response to induction chemotherapy in patients suffering from high-risk neuroblastoma." (PMID 31803613, 2019). "Because the GRD R1276P mutant specifically disrupts the ability of the GRD to mediate the NF1 GAP activity, this result indicates that NF1 normally suppresses the development of neuroblastoma by downmodulating oncogenic signals from RAS." (PMID 27130733, 2016). "In particular, neuroblastomas can occur when a protein called MYCN is over-produced and a tumor suppressor protein called NF1 is lost." (PMID 27130733, 2016).
neuroblastoma (continued). "We also show that the very aggressive growth properties of MYCN-induced neuroblastomas with loss of nf1 are due to aberrant activation of RAS signaling, because the increased penetrance and rapid growth could be suppressed by overexpressing the intact NF1 GRD domain." (PMID 27130733, 2016). "Therefore, our findings reveal a number of novel points of functional cross-talk between MYCN and the MAPK signalling pathway, suggesting that ERK inhibition could be a viable target not only for NF1 mutated, but neuroblastoma in general including MNA neuroblastoma." (PMID 26673823, 2015). "In contrast to our observations of ALK mutations co-occurring with NF1 or activating RAS mutations, these mutations were mutually exclusive in neuroblastoma samples from patients not treated with ALK inhibitors." (PMID 35689207, 2022). "Cell lines sensitive to MEK inhibitors, however, show only a weakened or absent negative ERK to RAF feedback, which we propose as the mechanistic reason for MEK inhibitor sensitivity in neuroblastoma cell lines lacking NF1." (PMID 35689207, 2022). "In conclusion, only NF1 loss but not the expression of oncogenic NRASQ61K seems to trigger loss of feedback-mediated MEK reactivation and leads to increased sensitivity of neuroblastoma cell lines harboring ALK mutations to MEK inhibition." (PMID 35689207, 2022). "Moreover, our results from survival analyses reveal the prognostic value of PBX1, NF1, and HOXC9 expression in neuroblastoma tissue." (PMID 31803613, 2019). "MEKi treatment is known to decrease NF1 associated overactive MAPK signaling and to restore retinoic acid sensitivity in NF1 lacking neuroblastoma cells." (PMID 29131833, 2017). "In a previous study the transcriptional co-activator ZNF423 was suppressed in neuroblastoma cells lacking NF1 due to overactive MAPK cascade signaling, finally leading to ATRA resistance." (PMID 29131833, 2017). "Thus, our inability to demonstrate increased GTP on RAS in NF1-deficient neuroblastoma cell lines may reflect the strong activation of the RAS-MAPK signaling pathway in essentially all high-risk neuroblastomas, if not by NF1 loss then by direct mutation of RAS itself or other types of mutations." (PMID 27130733, 2016). "NF1 gene expression, but not MEK1 or MEK2 gene expression, was strongly associated with patient outcomes in neuroblastoma and appeared to have prognostic effects independent of tumor stage." (PMID 26925841, 2016). "Gene expression of NF1, but not MEK1, correlated with patient outcomes in neuroblastoma, and NF1 protein expression also correlated with responses to binimetinib." (PMID 26925841, 2016). "Gene expression of NF1 and MEK1 was examined in relationship to neuroblastoma patient outcomes." (PMID 26925841, 2016). "Additionally, we analyzed a transcriptional co-activator for retinoic acid receptors, ZNF423, which has been described to be lost in human NF1 lacking neuroblastoma cells." (PMID 29131833, 2017). "Furthermore, recent studies have identified a potential role for the Ras-GTPase activating protein (RasGAP) NF1 as a mediator of CRA resistance in neuroblastoma cells, suggesting key roles for the RAS/MAPK pathway both in neuroblastoma differentiation and relapse." (PMID 26925841, 2016). "To test whether functional interactions between NF1 and ALK exist in human cells, we used the SK-SY5Y and Kelly neuroblastoma cells, both of which harbor constitutively active F1174L ALK alleles, and both of which are highly sensitive to pharmacological ALK inhibition." (PMID 24278035, 2013). "Thus, GAP-independent activities of NF1 appear to restrict the growth of normal neural crest-derived tissues during development, as the PSNS overgrowth phenotype was not rescued by the same level of GRD restoration that suppressed the accelerated onset of MYCN-driven neuroblastoma." (PMID 27130733, 2016).
neuroblastoma (continued). "Previous work has identified NF1 gene deletions in multiple neuroblastoma cell lines, likely contributing to the lack of NF1 protein seen in these cell lines and suggesting that neuroblastoma tumors with reduced or absent NF1 expression are likely to be sensitive to MEK inhibition." (PMID 26925841, 2016).
autism (44 papers, 2011 to 2025). Persistent deficits in social interaction and communication and interaction as well as a markedly restricted repertoire of activity and interest as well as repetitive patterns of behavior. "Several studies have confirmed that the (AAAT)n repeat polymorphism in the Alu sequence of the Neurofibromatosis-1 (NF1) gene is related to racial differentiation in autism patients and has a regulatory effect on gene expression." (PMID 37370452, 2023). "Such analyses are key to refining our use of autism diagnostic tools in NF1 and will be essential to progress our understanding of the autistic phenotype in children with NF1." (PMID 34983638, 2022). "Other studies have suggested roles in neuronal differentiation and function, with a CRLF3 variant associated with the extent of autism in NF1 patients." (PMID 35795682, 2022). "Neurofibromatosis 1 (NF1) is a single-gene disorder associated with cognitive phenotypes common to neurodevelopmental conditions such as autism." (PMID 36316421, 2022). "Simvastatin demonstrated specific effects in key brain areas associated with the NF1 neural pathology in previous studies that are highly associated with social impairment and autism psychopathology." (PMID 34947895, 2021). "A specific role in the development of the NF1 microdeletion-associated phenotype and in particular autism has recently been demonstrated for the cytokine receptor-like factor 3 (CRLF3) gene located within the NF1 microdeletion region." (PMID 34681033, 2021). "It is also the first trial that has looked in detail at statin effects on ‘upstream’ process at cell and neural system levels, reflecting a pathogenic pathway between gene disruption and the autism-related behavioural psychopathological outcomes known in NF1." (PMID 29484149, 2018). "This has future potential for insights into causal pathogenesis in autism and NF1 as well as suggesting more focused treatment targets." (PMID 29484149, 2018). "Some of the oncogenes and tumor suppressor genes like PTEN and NF1 are implicated in causing hereditary cancer susceptibility syndromes overlap with those involved in autism." (PMID 28983852, 2017). "Genes in proximity to these CGs include NF1, whose dysfunction is strongly associated with syndromic autism." (PMID 24875834, 2014). "NF1 encodes a neurofibromin responsible for signal transduction, and has been associated with mental retardation and autism." (PMID 22373040, 2011). "Another gene with an intronic SNP, nuclear factor 1 X-type (Nf1) is characterized as a “Syndromic” autism gene, meaning its dysfunction is associated with the development of autistic traits that are not typically associated with a conventional autism diagnosis." (PMID 40956789, 2025). "In addition, precise delineation of core autistic behaviours is a crucial step for the establishment of genotype–phenotype associations in NF1 that holds promise for advancing our understanding of the causal mechanisms of autism." (PMID 34983638, 2022). "This discrepancy likely reflects that the ARRA Autism Sequencing Collaboration cohort we used contains few syndromic cases (e.g., autistic patients with syndromic mutations in tumor suppressor genes, such as NF1, PTEN, TSC1/2)." (PMID 26934580, 2016). "In addition, genes involved in learning and memory (ARHGAP39 and HERC1), intellectual disability (SOBP), or autism (NF1), whose mutations cause neurodevelopmental, behavioral, learning, and motor abnormalities, are repressed by exercise and normalized or slightly induced upon subsequent rest." (PMID 40725218, 2025). "Further exploration by comparisons of all algorithm items separately found that on almost all the SA algorithm items the NF1+ASD group had significantly higher scores than the autism spectrum group, but significantly lower scores on Unusual eye contact." (PMID 38581124, 2024).
autism (continued). "A single deleterious CRLF3 missense mutation (c.1166T > C, p.Leu389Pro) was recurrently identified in NF1 children with higher SRS-2 scores for autism evaluation." (PMID 38448973, 2024). "At 36 months, 31% of participants in the NF1 group scored above threshold for autism on the ADOS-2 or BOSA." (PMID 39407332, 2024). "The parents themselves are at higher risk of having social communication and interaction difficulties, due to established higher rates of autism in individuals with NF1." (PMID 39407332, 2024). "In summary, this study characterises the core features of autism in children with NF1, with findings suggestive of a distinct autistic phenotype that has not been previously reported." (PMID 34983638, 2022). "As a single-gene condition with high autism penetrance, NF1 presents a valuable genetic model for advancing our understanding of the neurobiological mechanisms of autism." (PMID 34983638, 2022). "As such, this between-study discrepancy is most appropriately viewed as a cohort effect and future studies are needed to help determine the weight of evidence for the prominence of atypical eye contact in children with NF1-related autism." (PMID 34983638, 2022). "NF1 is also relevant for understanding pathways to autism because the condition is characterised by an elevated prevalence of autism outcomes (> 40%))." (PMID 36482366, 2022). "We compared the phenotypic profile of NF1 + ASD (n = 48), NS + ASD (n = 11), and CFC + ASD (n = 7) on the Autism Diagnostic Inventory (ADI-R) and the Autism Diagnostic Observation Schedule (ADOS)." (PMID 33519543, 2020). "The most direct evidence comes from monogenic, syndromic forms of autism, many of which are caused by lost or reduced function in genes, including eIF4E, FMR1, PTEN, NF1, TSC1, TSC2 and PRKCB1, that negatively regulate the pathway or its subsystems." (PMID 31548888, 2019). "The presence of microstructural abnormalities, reflected in increased ADC values, have also been described beyond NF1 in idiopathic autism and potentially give these findings wider relevance in relation to this NF1-autism cohort." (PMID 29484149, 2018). "It is the key inducer of the familial cancer syndrome, NF-1, a pathology where autism-like social dysfunction has also been observed." (PMID 28420080, 2017). "It is hypothesised that having a parent with NF1 (who are themselves at higher likelihood of having autism, ADHD and cognitive difficulties) is likely to impact the cognitive, behavioural and social development of the child." (PMID 39407332, 2024). "Data on ASD symptomatology (Autism Diagnostic Observation Scale (ADOS-2) & Social Responsiveness Scale (SRS-2)) were collected from children and adolescents with FXS (n = 54), AS (n = 93), TSC (n = 112), and NF1 (n = 278)." (PMID 39395123, 2024). "Apart from vision, all sensory modalities are affected, and the NF1 sensory processing profile is broadly similar to children with autism and ADHD, showing avoiding, sensitivity, registration, and seeking difficulties, although to different degrees of severity." (PMID 37509275, 2023). "Importantly, these signalling pathways offer potential molecular targets for disease-directed pharmacological treatments in NF1 that have, so far, been elusive for idiopathic autism." (PMID 34983638, 2022). "To address the debate around whether features of autism in NF1 are driven by the broader NF1 neurodevelopmental phenotype, we also explored associations between autistic behaviours and cognitive, language, and behavioural comorbidities in our NF1 cohort." (PMID 34983638, 2022).
autism (continued). "It is worth noting that in this trial, the effects of simvastatin on the upstream processes at the cell and neural system levels were studied in detail, reflecting a relationship between gene disruption and the autism-related behavioral psychopathological outcomes known in NF1." (PMID 34947895, 2021). "Autism-related symptoms also appear to be very frequent in patients with NF1 microdeletions." (PMID 34681033, 2021). "Important candidate genes (e.g., PTEN, NF1, and BRCA2) are found meeting criteria clearly associated with predisposition to cancer such as colorectal, other gastrointestinal tumors, and breast reported in the top seven autism and cancer-associated diseases." (PMID 30866437, 2019). "Loss of function in multiple genes that negatively regulate mTOR, including TSC1, TSC2, PTEN, NF1, and FMR1, has been linked to syndromic autism with increased head size and high rates of seizures; both of these traits are also found in mice heterozygous for AMBRA1 loss of function." (PMID 31687209, 2019). "Neurofibromatosis 1 (NF1) is a monogenic model for syndromic autism." (PMID 29484149, 2018). "This functional localisation may thus be relevant both to the high autism prevalence in NF1 and to how simvastatin could have specific remedial effects on NF1-autism at the level of brain structure and function." (PMID 29484149, 2018). "Consequently, the study of monogenic disorders related to autism, such as neurofibromatosis type 1 (NF1), represents a promising approach to isolate mechanisms underlying ASD-related cognitive disabilities." (PMID 28932379, 2017). "Moreover, although NF1 is well recognized as a single-gene model for autism, this notion should be put into the context of the large heterogeneity of ASD." (PMID 28932379, 2017). "This approach has recently been taken with regard to neuroimaging phenotypes in 26 mouse models recapitulating features of autism spectrum conditions (including the 39,XO mouse), and could feasibly be undertaken with existing rodent models for TS, NF1 and NS." (PMID 28694877, 2017). "However, in one study higher quantitative autism traits were detected in NF1 subjects with a variant at the 3′ end, as opposed to variants at the 5′ end of the NF1 gene." (PMID 38581124, 2024). "While heterozygosity for a germline NF1 mutation has biological consequences, such as learning and attention deficits, and autism, a single NF1 mutation is not sufficient for tumor formation." (PMID 35188187, 2022). "At the molecular level, mutations in the NF1 gene lead to hyperactivation of the Ras-mitogen-activated protein kinase (MAPK) pathway as well as disinhibition of mechanistic target of rapamycin (mTOR) kinase signalling, both of which have been implicated in the pathogenesis of autism." (PMID 34983638, 2022). "While the frequent co-occurrence of autism with other neurodevelopmental disorders is well established and formally recognised by DSM-5 criteria, the careful examination of associations between autistic behaviours and other NF1 characteristics is essential for improving diagnostic accuracy in NF1." (PMID 34983638, 2022). "This confirms previous genetic studies suggesting that defects in the PI3K/mTOR pathway may be a shared pathomechanism in a sub-cohort of individuals with autism, in addition to the known syndromic cases associated with altered PI3K/mTOR signaling (such as FXS, TS, and NF-1)." (PMID 26770665, 2016). "Similarly, nuclear factor 1 X-type (Nf1) is characterized as a “Syndromic” autism gene, meaning its dysfunction is associated with the development of autistic traits that are not typically associated with a conventional autism diagnosis." (PMID 40956789, 2025). "Nine (53%) had at least one NF1-related complication; scoliosis, hypertension, ADHD, learning disability, language delay, autism and delay in gross and fine motor function development." (PMID 33853649, 2021).